OAS2 (2'-5'-oligoadenylate synthetase 2)
Diseases named in the same sentence as OAS2 in open-access papers (continued):
Sharing a sentence is not in itself a finding about the gene and the disease.
psoriasis (continued). "Additionally, the utilization of biological agents resulted in the suppression of serum OAS2 and OAS3 at low levels, along with an elevation in the serum OAS1 level among patients with psoriasis." (PMID 38298734, 2024). "Thus, serum markers of psoriasis patients using different biologics, including OAS1, OAS2, and OAS3, were also tested." (PMID 38298734, 2024). "This study suggested that during the COVID-19 pandemic, ADA, SEC, and IXE may suppress serum OAS2 and OAS3 levels in patients with psoriasis, thereby preventing psoriasis exacerbation." (PMID 38298734, 2024). "In addition, the use of biological agents may suppress the serum OAS2 and OAS3 at low levels and elevate the serum OAS1 level in patients with psoriasis." (PMID 38298734, 2024).
ZIKV infection (9 papers, 2017 to 2025). "Several studies have underscored the importance of OAS2 in controlling viral replication, including ZIKV infection." (PMID 39940721, 2025). "We found that ZIKV infection significantly induced OAS2 expression by ~12.9-fold at MOI of 20 in 2FTGH cells and by ~1.9-fold in U5A cells." (PMID 32276512, 2020). "We also found that ZIKV infection induced the expression of OAS2, as well as OAS1 and OAS3 in A549 cells." (PMID 32276512, 2020). "We selected OAS2, the significantly up-regulated gene induced by ZIKV infection for further investigation." (PMID 32276512, 2020). "The results showed that ZIKV infection significantly increased OAS2, IFIT3 and IFITM1 levels, and decreased Clorf27, DLG1 and EHBP1 levels." (PMID 32276512, 2020). "In this study, we sought to investigate the effect of ZIKV infection on OAS2 expression and to explore the role of OAS2 in ZIKV replication and its underlying mechanism." (PMID 32276512, 2020). "In conclusion, ZIKV infection induced OAS2 expression, which in turn inhibited ZIKV replication through activating the IFN-induced Jak/STAT signaling pathway." (PMID 32276512, 2020). "OAS2 expression can be directly induced through RIG-I or indirectly induced through type I IFN pathway following ZIKV infection." (PMID 32276512, 2020). "For example, expression of OAS2, the most upregulated gene during persistent infection, increased 2000-fold in response to ZIKV infection." (PMID 30453621, 2018). "Next, we used IFNAR-deficient U5A cells and its parental 2FTGH cells to further assess whether ZIKV infection induced OAS2 expression through an IFN-dependent pathway." (PMID 32276512, 2020). "As OAS2 is an interferon stimulated gene, we next investigated whether ZIKV infection induces OAS2 expression through increased type I IFN production and enhanced activation of type I IFN pathway." (PMID 32276512, 2020). "In addition, we also confirmed the anti-ZIKV effect of OAS2 by transfecting OAS2 plasmid before ZIKV infection, and a similar inhibitory effect was observed." (PMID 32276512, 2020). "As RIG-I and OAS2 are ISGs, we speculated that ZIKV infection induced the production of ISGs, such as OAS2, partially dependent on the integrity of the type I IFN signaling pathway." (PMID 32276512, 2020). "At 36 h post-ZIKV infection, the expression levels of interferon-induced antiviral proteins, including ISG15, ISG56, OAS1, OAS2, and OAS3, were increased by TRIM38 overexpression and decreased by TRIM38 knockout." (PMID 40006954, 2025). "Generation of innate AVPs, including OAS1, OAS2, OASL, and MX1, in response to IL27 was found to be protective against Zika virus infection in human keratinocytes." (PMID 37310504, 2023). "Compared to A549 cells, induction of innate immune genes especially IFN-λ2 and OAS2 during ZIKV infection was significantly lower in Sertoli cells regardless of whether African or American strains of ZIKV were used for infection." (PMID 29615760, 2018). "We found that OAS2 overexpression activated the Jak/STAT signaling as shown by the increased level of p-STAT1, enhanced ISRE activity and up-regulated expression of several ISGs in A549 cells with and without ZIKV infection." (PMID 32276512, 2020).
colorectal cancer (7 papers, 2018 to 2024). A primary or metastatic malignant neoplasm that affects the colon or rectum. "High OAS2 expression was shown to associate with better prognosis in breast, bladder and colorectal cancer." (PMID 36900319, 2023). "Moreover, ATG101 is essential for tissue homeostasis in both adult brains and midguts and mediates GSN and OAS2, which are positively and negatively associated with the recurrence of colorectal cancer, respectively." (PMID 35592424, 2022). "OAS2 expression has been associated with better patient prognosis, highlighting the potential of OAS genes as therapeutic targets in colorectal cancer." (PMID 39633486, 2024). "For example, it was reported that OAS2 suppressed cell proliferation and invasion and promoted autophagy in colorectal cancer." (PMID 39416786, 2024). "In contrast, studies on other cancer types, such as lung and colorectal cancer, have observed OAS gene mutations, particularly in OAS1 and OAS2, though these alterations are relatively rare." (PMID 39633486, 2024). "Similarly, in colorectal cancer, OAS genes, particularly OAS2, have been linked to immune surveillance and tumor progression." (PMID 39633486, 2024). "In tumors, OAS2 upregulates the expressions of E-cadherin, β-catenin, claudin-1, and snail, induces autophagy, and prolongs recurrence-free survival (RFS) in colorectal cancer." (PMID 36471952, 2022).
systemic lupus erythematosus (7 papers, 2015 to 2024). An autoimmune multi-organ disease typically associated with vasculopathy and autoantibody production. "Expression of OAS2 in a triad panel with two other immune response genes was found to be diagnostic of systemic lupus erythematosus (SLE), discriminating between SLE positive subjects and normal controls with 94 % sensitivity." (PMID 26979060, 2016). "OAS2 was among a limited set of genes upregulated in T cells of individuals with systemic lupus erythematosus (SLE), and this limited set of genes was able to reliably differentiate SLE from healthy controls and was associated with disease activity." (PMID 33916486, 2021). "OAS2 can also be considered as biomarker gene for systemic lupus erythematosus (SLE) diagnosis." (PMID 34926448, 2021).
autoimmune disease (6 papers, 2010 to 2022). A disorder resulting from loss of function or tissue destruction of an organ or multiple organs, arising from humoral or cellular immune responses of the individual to their own tissue constituents. "MX1 and OAS2 were also detected in the blood of patients with an autoimmune disease, namely systemic lupus erythematous disease, in which their roles were not totally defined." (PMID 30374345, 2018). "Additionally, in agreement with a local immune suppression environment, IFIT1, OAS1 and OAS2 are up-regulated in the autoimmune disease systemic lupus." (PMID 20707927, 2010). "Particularly, in a study it has been proposed a three gene-expression panel that included IL10, OAS2, and CD70 genes that, according to the authors, were able to differentiate SLE patients from control subjects and from patients with other autoimmune diseases." (PMID 36428917, 2022). "In particular, a previous study proposed a T cell gene expression panel including the OAS2, CD70, and IL10 genes as useful biomarkers for SLE discrimination from other autoimmune diseases and for the monitoring of disease activity." (PMID 36428917, 2022).
melanoma (6 papers, 2017 to 2026). A malignant, usually aggressive tumor composed of atypical, neoplastic melanocytes. "qPCR analysis of endogenous gene expression in mouse melanoma cells with Imp1-3 gene knockouts (no cytokine’s treatment) showed an increase of ISGs levels (e.g., Rig-1, Ifi44, Irf7/9, Oas2)." (PMID 37503349, 2023). "Additionally, our study identified genes without reported expression in CMM and nevi or biological function related to melanoma progression, including CCL3L3, NPY1R, IL11A, FCGR1B, OAS2, ASB11, FCGR3A, and GLA." (PMID 35008167, 2021).
dengue (5 papers, 2012 to 2024). "OAS1 is induced earlier than OAS2 and OAS3 during dengue virus infection, and mutations of the different OAS members had been correlated with several viral infections." (PMID 37209263, 2023). "When comparing controlled versus hemorrhagic dengue (GSE18090, unpublished data), we found that the individual expression of ISG15, OASL, OAS2 and TNFSF10 can be used to anticipate the complication status of dengue infection into a hemorrhagic outcome." (PMID 26302899, 2015). "Despite the different conditions in vivo, with shifting cell populations and multiple interacting stimuli, 57 of these genes, including canonical ISGs such as ISG15, ISG20, OAS2, ISI27, STAT1 and STAT2, had consistently elevated transcript levels in dengue patients compared to healthy controls." (PMID 23285306, 2012).
HIV-1 infection (5 papers, 2017 to 2023). The type species of lentivirus and the etiologic agent of acquired immunodeficiency syndrome (AIDS). "HIV-1 infection of pericytes significantly upregulated expression of all OAS genes at the mRNA level but selectively OAS1, OAS2 and OAS3 at the protein level." (PMID 36778388, 2023). "There was a significant increase in the expression of OAS2 and OAS3 proteins 24, 48, or 72 h post HIV-1 infection; however, these changes were more prominent for OAS 2 than those for OAS3." (PMID 37209263, 2023). "Most interestingly, silencing of OAS1, OAS2, OAS3, or OASL markedly increased HIV-1 replication in human brain pericytes, providing the first evidence that the OAS family can regulate HIV-1 infection in human pericytes." (PMID 37209263, 2023).
influenza (5 papers, 2011 to 2024). An acute viral infection of the respiratory tract, occurring in isolated cases, in epidemics, or in pandemics; it is caused by serologically different strains of viruses (influenzaviruses) designated A, B, and C, has a 3-day incubation period, and usually lasts for 3 to 10 days. "Specifically, influenza samples maintained higher levels of type I IFN response–associated antiviral ISGs (e.g., IFITM1, IFITM2, IFITM3, OAS2, OAS3, OASL) and antigen presentation genes (e.g., HLA-DRB5, HLA-C, B2M, HLA-B, HLA-E)." (PMID 34618691, 2021). "In contrast, several genes involved in the interferon-stimulated innate immune response (OAS1, OAS2, SOCS1, DDX58, 16 CXCL10) were upregulated following influenza superinfection during SARS-CoV-2 infection." (PMID 38178911, 2023).
gastric cancer (4 papers, 2019 to 2024). A primary or metastatic malignant neoplasm involving the stomach. "In trastuzumab-resistant gastric cancer, OAS1, OAS2, OAS3, and OASL were all identified as key genes." (PMID 38380081, 2024). "OAS1, OAS2, OAS3, and OASL have been recognised as pivotal genes in a bioinformatic study focusing on trastuzumab-resistant gastric cancer." (PMID 36567857, 2022). "Our previous research indicated that OAS1, OAS2, OAS3 and OASL were all identified as hub genes from the protein-protein interaction network of differentially expressed genes between the trastuzumab-resistant gastric cancer and control groups." (PMID 32560641, 2020).
asthma (3 papers, 2018 to 2022). "The association of OAS2 with asthma was reported in an earlier GWAS." (PMID 35386719, 2022).
Autoimmunity (3 papers, 2015 to 2022). The occurrence of an immune reaction against the organism's own cells or tissues. "Our mRNA analysis identified new genes related to T cell dysfunction and confirmed induction of interferon signature genes (ISG), including OAS2 which we previously showed is specific to SLE autoimmunity." (PMID 26544975, 2015).
breast tumors (3 papers, 2015 to 2024). "Protein biomarkers such as S100A2, OAS2 and/or IFNβ RNA expression in breast tumors may prove to be useful guides in predicting the response of IFN-positive patients to anti-interferon therapeutics." (PMID 25884794, 2015). "Taken together, these findings underscore the distinct expression patterns of OAS1, OAS2, OAS3, and OASL in breast tumors across a spectrum of immune and molecular subtypes." (PMID 39633486, 2024).
glioma (3 papers, 2019 to 2024). A benign or malignant brain and spinal cord tumor that arises from glial cells (astrocytes, oligodendrocytes, ependymal cells). "Expression of ISGs MX1, XAF1, or OAS2 strongly correlated with MAP3K7 dependency in DepMap glioma lines and this correlation was still present, but weaker, in 930 non-glioma cell lines." (PMID 38632238, 2024). "Genes, such as OAS2, ULBP1, HERPUD1, and CASP4, are diagnosed with the growth of various cancers, such as oral cancer, cervical cancer, and gliomas, but these genes may identify with the development of BRCA." (PMID 31311202, 2019).
Hepatitis (3 papers, 2021 to 2024). Inflammation of the liver. "Non-treated HBs-Tg mice showed higher baseline expression of XBP1s, phos-PERK, CHOP and ISGs (ISG15 and OAS2) in association with mild liver injury (sALT 100–300 U/L) than non-treated WT mice suggesting that HBsAg accumulation triggered UPR activation in association with mild spontaneous hepatitis." (PMID 33979382, 2021).
lung adenocarcinoma (3 papers, 2020 to 2025). A carcinoma that arises from the lung and is characterized by the presence of malignant glandular epithelial cells. "OAS1 overexpression influenced survival and immune cell infiltration in patients with lung adenocarcinoma and OAS2 was shown to participate in a sustained senescence response of human primary melanocytes upon repeated UVB exposure." (PMID 40312750, 2025). "Furthermore, we detected the mRNA expression levels of DUXAP10 and OAS2 in 25 lung adenocarcinoma patients before and after gefitinib treatment." (PMID 36471952, 2022).
measles (3 papers, 2022 to 2025). A highly contagious viral infection caused by the measles virus. "In the cases of RNA viruses, including influenza A, measles, and coronavirus disease, downregulation of genes such as Ddx58, Il1b, Stat1, Stat2, Oas3, Oas2, Oas1a, Oas1g contributes to increased susceptibility to infections." (PMID 40206211, 2025).
oral cancer (3 papers, 2018 to 2021). "This hypothesis was supported by recent studies, which indicated that human OAS2 downregulated the expression of T-cell receptor CD-ξ chain via caspase-3 activation in oral cancer." (PMID 30587119, 2018).
rheumatoid arthritis (3 papers, 2019 to 2024). A chronic, systemic autoimmune disorder characterized by inflammation in the synovial membranes and articular surfaces. "These genes, OAS2, MX1, and MX2, have been linked to the response of immunological pathways in rheumatoid arthritis and periodontitis." (PMID 38323815, 2024).
AIDS (2 papers, 2016 to 2019). A syndrome resulting from the acquired deficiency of cellular immunity caused by the human immunodeficiency virus (HIV). "Additionally, novel SNPs that associated with progression from HIV infection to AIDS were identified in OAS2 and OAS3 genes." (PMID 28050553, 2016). "Additionally, SNPs that associated with progression from HIV infection to AIDS were identified in two 2′-5′-oligoadenylate synthetase genes (OAS2 and OAS3)." (PMID 28050553, 2016).
atherosclerosis (2 papers, 2025). A disease characterized by the build-up of fatty material and calcium deposition in the arterial wall resulting in partial or complete occlusion of the arterial lumen. "While earlier works emphasized well-known inflammatory markers (e.g., IL6, TNF-α), we identified novel candidates (OAS2, TMEM106A, ABCB1) with limited prior links to atherosclerosis or stroke." (PMID 40371070, 2025). "By integrating machine learning with multi-omics bioinformatics, we established a novel three-gene signature (OAS2, TMEM106A, ABCB1) for precise diagnosis of atherosclerosis and ischemic stroke." (PMID 40371070, 2025). "Using a Venn diagram to identify the shared genes, we identified six candidate downstream molecules potentially regulated by AP‐1 and involved in vascular endothelial dysfunction and atherosclerosis induced by OSS: NR4A1, ZNF467, LGAL59, OAS1, OAS2, and TGM2." (PMID 40492401, 2025).
cervical cancer (2 papers, 2019 to 2025). A primary or metastatic malignant neoplasm involving the cervix. "The analysis showed that OAS2, KLHDC7B, STAT1, TYMP, PSME2 and GBP5 were significantly upregulated in cervical cancer cells compared with normal epithelial cells." (PMID 40259929, 2025).
hepatocellular carcinoma (2 papers, 2021 to 2024). A malignant tumor that arises from hepatocytes. "Moreover, OAS2 was monitored to be highly enriched and overexpressed in the hepatitis C virus-infected hepatocellular carcinoma." (PMID 34516354, 2021). "In hepatocellular carcinoma (HCC), OAS family genes, particularly OAS1 and OAS2, play a role in the tumor immune response." (PMID 39633486, 2024).
Herpes simplex infection (2 papers, 2022 to 2024). "The KEGG pathway analysis highlighted that a large number of genes that were up-regulated after infection with V2 were the same as those upregulated in response to Herpes simplex infection (genes Myd88, Irf7, H2-Q7, Casp8, Tlr3, Daxx, C3, H2-Aa, Oas2, Oas3, H2-T22, H2-T23 and Cd74)." (PMID 35458422, 2022). "We also found a certain positive relationship between OAS2, CXCL10, and herpes simplex infection." (PMID 39091676, 2024).
interstitial lung disease (2 papers, 2016 to 2022). A diverse group of lung diseases that affect the lung parenchyma. "A number of genes, such as Bst2, Rsad2, Ifi44, Oas2 and Stat2, were previously found to be downregulated in pulmonary fibroblasts from IPF patients and from scleroderma-associated interstitial lung disease." (PMID 27428020, 2016). "Some studies have suggested that OASL and OAS2 are upregulated in PBMCs and skin tissue of SSc patients, and OAS family genes are also increased in CD31+/CD102+ lung microvascular endothelial cells from SSc patients with end-stage interstitial lung disease." (PMID 35183246, 2022).
liver disease (2 papers, 2017 to 2019). "In this way, OAS1 rs2285934 and OAS2 rs1293762 polymorphisms could increase expression of OAS1 and OAS2, improving the control of HCV, and might therefore be related to the decrease of sustained inflammation and progression of liver disease." (PMID 28139728, 2017).
lupus nephritis (2 papers, 2021 to 2023). Glomerulonephritis in the context of systemic lupus erythematosus. "OAS family genes including OAS2 were revealed to be closely related to lupus nephritis." (PMID 34926448, 2021). "Moreover, OAS1, OAS2, and OAS3 were closely related to lupus nephritis (LN) progression." (PMID 36655136, 2023).
mastitis (2 papers, 2017 to 2022). Inflammation of breast tissue during lactation or postpartum due to an obstructed duct or infection. "As we show, stimulation of the OAS2 pathway can produce the accepted cause of mastitis, milk stasis, opening a new avenue of investigation into human mastitis as a disease amenable to anti-inflammatory therapy." (PMID 29117179, 2017). "In the present study, genes NOD2, CXCL8, OAS2, and TLR4 were differentially expressed in the blood transcriptome of subclinical mastitis cows and involved in the NOD-like receptor, Toll-like receptor pathway and were identified as key candidates for this study." (PMID 36204322, 2022).
mesothelioma (2 papers, 2022 to 2025). A usually malignant and aggressive neoplasm of the mesothelium which is often associated with exposure to asbestos.